NAMPT (nicotinamide phosphoribosyltransferase)
Diseases named in the same sentence as NAMPT in open-access papers (continued):
Sharing a sentence is not in itself a finding about the gene and the disease.
lung fibrosis (7 papers, 2022 to 2026). "The body weight and survival curves showed conditional knockout of NAMPT in monocytes/macrophages markedly slowed weight loss and improved survival rate in mice with lung fibrosis." (PMID 38773984, 2024). "To clarify the underlying mechanism of the NAMPT in monocytes/macrophages regulating lung fibrosis injury in mice, we detected macrophage polarization in the lungs of BLM-treated WT and NAMPT cKO mice." (PMID 38773984, 2024). "Enrichment analysis of the DEGs and protein–protein interaction analysis using String database demonstrated an association of HBEGF and NAMPT together with proteins involved in inflammatory and lung fibrosis pathways." (PMID 36388923, 2022). "Here, we ultimately confirmed that in BLM-induced mouse pulmonary fibrosis, NAMPT at least partially promotes macrophage M2 polarization by activating STAT6, which was consist with the previous report that STAT6 mediated M2 programing." (PMID 38773984, 2024). "NAMPT inhibitor FK866 alleviated BLM-induced pulmonary fibrosis in mice and significantly reduced NAMPT levels in bronchoalveolar lavage fluid (BALF)." (PMID 38773984, 2024). "Here, our in vivo and in vitro experiments confirmed that during the process of pulmonary fibrosis, NAMPT expression was upregulated, and NAMPT release was increased in the lung, promoting the progression of pulmonary fibrosis." (PMID 38773984, 2024). "We investigated the role and mechanism of NAMPT in lung fibrosis by using pharmacological inhibition on NAMPT and Nampt transgenic mice." (PMID 38773984, 2024). "To our knowledge, we, for the first time, confirm that NAMPT is an essential mediator in regulating the transformation of monocytes/macrophages to pro-fibrotic phenotype in the process of pulmonary fibrosis." (PMID 38773984, 2024). "Here, we found that conditional knockout of NAMPT in monocytes/macrophages (NAMPT cKO) corrected the dysregulated polarization of infiltrating macrophages, significantly improving lung fibrosis damage and survival in mice." (PMID 38773984, 2024). "In contrast, many cells including AT2 cells, downregulate NAMPT expression during pulmonary fibrosis." (PMID 38773984, 2024). "In this study, we found that NAMPT was upregulated and released from macrophages during pulmonary fibrosis." (PMID 38773984, 2024). "Knocking out NAMPT in mouse monocytes/macrophages (Namptfl/fl;Cx3cr1CreER) significantly alleviated BLM-induced pulmonary fibrosis in mice, decreased NAMPT levels in BALF, reduced the infiltration of M2 macrophages in the lungs and improved mice survival." (PMID 38773984, 2024). "NAMPT deficiency impaired AT2 renewal and enhanced lung fibrosis through downregulation of SIRT7 and SOD2, which resulted in increased oxidative stress, mitochondrial dysfunction, accumulated aberrant transitional cells, and impaired differentiation from AT2 to alveolar type 1 (AT1) cells." (PMID 42096291, 2026). "NAMPT inhibition in macrophages might be a novel approach for preventing and treating pulmonary fibrosis." (PMID 38773984, 2024). "In summary, our study revealed that NAMPT prompts pulmonary fibrosis by driving macrophage M2 polarization in an enzymatic-independent, STAT6-dependent manner; furthermore, our study paves the way to develop novel anti-pulmonary fibrosis strategies based on deletion of NAMPT in macrophage." (PMID 38773984, 2024). "NAMPT is suggested to serve as a biomarker for pulmonary fibrosis." (PMID 38773984, 2024). "To determine the NAMPT level changes in patients with pulmonary fibrosis, we searched and retrieved three sets of transcriptomic data (GSE72073, GSE53845, GSE110147) from the GEO database and screened the differentially expressed genes (DEGs) in the lung between IPF patients and healthy donors (HD)." (PMID 38773984, 2024). "Furthermore, we clarified that extracellular NAMPT drives macrophage M2 polarization and promotes pulmonary fibrosis." (PMID 38773984, 2024).
lung fibrosis (continued). "Furthermore, we detected the NAMPT expression during pulmonary fibrosis at 7 days, 14 days, 21 days, and 28 days after BLM administration in mice, and we found that NAMPT expression peaked at 14-21 days when the lung injury and fibrosis became severe." (PMID 38773984, 2024). "However, the role of NAMPT in pulmonary fibrosis is controversial." (PMID 38773984, 2024). "NAMPT activation is a potentially promising therapeutic strategy for restoring AT2 progenitor cell function and halting or reversing progressive pulmonary fibrosis." (PMID 42096291, 2026). "Activation of NAMPT by small-molecule activators promoted IPF AT2 renewal and reversed lung fibrosis in WT mice." (PMID 42096291, 2026). "We found that the specific deletion of NAMPT in monocytes/macrophages inhibited M2 polarization and alleviated BLM-induced pulmonary fibrosis in mice, whereas supplementation of M2 macrophages restored the susceptibility of mice to BLM-induced injury." (PMID 38773984, 2024). "MSCs attenuate AT2 cells senescence by upregulating NAMPT expression and NAD+ levels, thus exerting protective effects in pulmonary fibrosis." (PMID 35012648, 2022). "In keeping with this notion, downregulation of nicotinamide phosphoribosyl transferase (NAMPT), a rate-limiting enzyme in NAD+ synthesis, has been shown to promote renal and lung fibrosis with increased collagen deposition and ECM remodeling." (PMID 35545049, 2022). "In vitro experiments confirmed that the mechanism of NAMPT engaged in pulmonary fibrosis is related to the released NAMPT by macrophages promoting M2 polarization in a non-enzyme-dependent manner by activating the STAT6 signal pathway." (PMID 38773984, 2024). "However, the role of NAMPT in pulmonary fibrosis has not been elucidated." (PMID 38773984, 2024).
myeloma (7 papers, 2014 to 2025). "NAMPT gene silencing also increased the sensitivity to bortezomib in myeloma, indicating NAMPT’s role in drug resistance." (PMID 35565188, 2022). "The involvement of NAMPT in myeloma progression was reported." (PMID 35565188, 2022). "Moreover, NAMPT gene knockdown by specific siRNA in multiple myeloma RPMI 8226 cells appeared to repress proliferation and induce apoptosis." (PMID 35565188, 2022). "Thus, using 17AAG (HSP90 inhibitor) + FK866 (NAMPT inhibitor) as proof of principle secDrugs, we established a novel pipeline to introduce several new therapeutic options for the management of PI and IMiD-resistant myeloma." (PMID 35264575, 2022). "This is in concordance with other studies in CLL and multiple myeloma cell lines where NAMPT protein levels and cytotoxic response to FK866 did not correlate." (PMID 28160567, 2017). "Importantly, a small molecule compound inhibitor of NAMPT, FK866 or APO866, was capable of triggering cytotoxicity in myeloma cells both in vitro and in vivo." (PMID 24690091, 2014).
non-small cell lung carcinoma (7 papers, 2014 to 2025). A group of at least three distinct histological types of lung cancer, including non-small cell squamous cell carcinoma, adenocarcinoma, and large cell carcinoma. "Non-small cell lung cancers (NSCLC) with excision repair cross-complementation group 1 (ERCC1) deficiency were exquisitely sensitive to NAMPT inhibitors, in vitro and in vivo." (PMID 32010616, 2019). "We next compared responses of SCLC and non-small cell lung cancer (NSCLC) lines to the NAMPT inhibitor (NAMPTi) FK866." (PMID 38092728, 2023). "The NAMPT mRNA expression and protein levels appeared to be significantly elevated in non-small-cell lung cancer cells with doxorubicin resistance." (PMID 35565188, 2022). "In non-small-cell lung cancer, the NAMPT levels in plasma were uncovered to correlate with the distant metastasis (p = 0.003) and the lymph node metastasis (p = 0.015)." (PMID 35565188, 2022). "To explore this we selected two non-small cell lung carcinoma cell lines that are sensitive to the NAMPT inhibitor GNE-617 (A549, NCI-H1334), one that shows intermediate sensitivity (NCI-H441), and one that is insensitive (LC-KJ)." (PMID 27711204, 2016). "In addition, NAMPT appeared to reduce doxorubicin sensitivity in non-small-cell lung cancer H1793 and A549 cells through the activation of Akt-ABCC1 signaling pathway." (PMID 35565188, 2022).
pulmonary hypertension (7 papers, 2019 to 2026). Increased pressure within the pulmonary circulation due to lung or heart disorder. "We show that miR410 targets the 3′ UTR of NAMPT and that, concomitant with NAMPT upregulation, miR410 is downregulated in lungs of mice exposed to hypoxia-induced pulmonary hypertension (HPH)." (PMID 31289307, 2019). "In this study, we aimed to study the regulation of NAMPT expression by microRNA410 (miR410) in hPAECs and explore the role of miR410 in the pathogenesis of experimental pulmonary hypertension." (PMID 31289307, 2019). "Inhibition of NAMPT is protective in preclinical models of pulmonary hypertension." (PMID 41648333, 2026). "NAMPT was recently suggested to play a role in pulmonary vascular remodeling, and NAMPT inhibition might be a potential therapeutic strategy for pulmonary arterial hypertension." (PMID 33488923, 2020). "The observed decrease in nicotinamide may be related to its higher use in the nicotinamide phosphoribosyltransferase reaction that promotes pulmonary vascular remodeling in the development of pulmonary arterial hypertension, a common finding in chronic hypoxia." (PMID 35145434, 2022). "The downregulation of miR-410 in hypoxia-prompted pulmonary hypertension (HPH) was first exhibited in a hypoxia-interceded HPH mouse model, and afterwards, the transfection of hPAECs with miR-410 imitators or inhibitors was studied to show that miR-410 directs the outflow of NAMPT in hPAECs." (PMID 40868164, 2025).
Alzheimer disease (6 papers, 2014 to 2022). A progressive, neurodegenerative disease characterized by loss of function and death of nerve cells in several areas of the brain leading to loss of cognitive function such as memory and language. "Thus, a decline of NAMPT in aging or age-associated Alzheimer’s disease (AD) brain may decrease NADH levels that in turn could cause an oxidized redox shift, lower GSH levels and promote neurodegeneration." (PMID 24655393, 2014). "In Alzheimer’s disease, the decrease of NAD+ levels has been shown to be associated with decreased activity of nicotinamide phosphoribosyltransferase (NAMPT)." (PMID 35057482, 2022). "A large number of studies have demonstrated that NAMPT participates in the pathophysiological changes of Alzheimer's disease, Parkinson's disease, cognitive function, spinal cord injury, axons degeneration, and cerebral ischemic stroke." (PMID 28097126, 2016). "Consequently, NMN treatment would bypass the decreased NAMPT activity in Alzheimer’s disease patients, which can be used as a potential treatment." (PMID 35057482, 2022).
bladder cancer (6 papers, 2014 to 2022). "In bladder cancer, a high serum NAMPT level was found to serve as a biomarker and an independent prognostic indicator." (PMID 32005247, 2020). "It has been reported that rs61330082 in NAMPT was statistically associated with risk for ARDS and rs2505568 was significantly associated with bladder cancer risk." (PMID 26389889, 2015). "Recent studies have identified NAMPT as a potential bladder cancer biomarker." (PMID 34329197, 2021).
endothelial dysfunction (6 papers, 2020 to 2025). In vascular diseases, endothelial dysfunction is a systemic pathological state of the endothelium (the inner lining of blood vessels) and can be broadly defined as an imbalance between vasodilating and vasoconstricting substances produced by (or acting on) the endothelium. "NAMPT overexpression alleviated ROS-associated endothelial dysfunction, VSMC proliferation and migration, and ECM reorganization." (PMID 33488923, 2020). "NAMPT was overexpressed through plasmid transfection, and cells were stimulated with Ang II for 48 hours to investigate the precise biological function of NAMPT in regulating Ang II-induced endothelial dysfunction." (PMID 33488923, 2020). "This adipokine exhibits nicotinamide phosphoribosyltransferase (NAMPT) activity, and as an intracellular form (iNAMPT) maintains the activity of NAD-dependent enzymes, such as sirtuin 1, while the extracellular form (eNAMPT) can induce inflammation and endothelial dysfunction." (PMID 34439776, 2021). "This impairment is reversed by either the NADPH oxidase inhibitor apocynin or by the nicotinamide phosphoribosyl transferase inhibitor APO866 but not by an insulin receptor-blocking antibody, suggesting that visfatin-induced endothelial dysfunction occurs via a NAMPT/NADPH pathway." (PMID 37190105, 2023).
Hyperglycemia (6 papers, 2018 to 2025). An increased concentration of glucose in the blood. "NAMPT is released by different cell types in response to cellular stress and inflammatory signals, such as hypoxia, starvation, hyperglycemia and pro-inflammatory cytokines." (PMID 39513038, 2024). "The figure shows the transition from normal physiology to hyperglycemia and diabetic nephropathy, highlighting increased CD38- and PARP1-mediated NAD+ consumption, compensatory NAMPT upregulation, and subsequent SIRT1 depletion leading to mitochondrial dysfunction and renal injury." (PMID 41470091, 2025).
liver cancer (6 papers, 2021 to 2025). An epithelial or non-epithelial malignant neoplasm that arises from the liver. "On the other hand, other studies involving the use of FK866 as an NAMPT inhibitor have shown that FK866 reduces the cell viability of other hepatic cancer cell lines in high doses (5–40 nM)." (PMID 40722609, 2025). "In liver cancer, it has been reported that silencing the expression of NAMPT can exceedingly inhibit PD-L1 immune checkpoint expression." (PMID 35776198, 2023). "Lastly, a recent paper first provided evidence for a direct functional correlation in liver cancer between the expression of PD-L1 and NAD-NAMPT axis, suggesting an association between NAMPT expression and an immune escape signature." (PMID 34073463, 2021). "In vitro studies show that FK866 induces apoptosis of liver cancer cells (HepG2) via highly specific, non-competitive inhibition of nicotinamide phosphoribosyltransferase (NAPRT)." (PMID 36658296, 2023).
Parkinson disease (6 papers, 2016 to 2025). A progressive degenerative disorder of the central nervous system characterized by loss of dopamine producing neurons in the substantia nigra and the presence of Lewy bodies in the substantia nigra and locus coeruleus. "Relative abundance of NAMPT was upregulated in blood of 99 early stage and drug-naïve PD patients compared to 101 healthy controls (HC) nested in the cross-sectional Parkinson’s Progression Markers Initiative (PPMI)." (PMID 27680512, 2016). "Along the same line of evidence, a NAMPT enzymatic activity enhancer, P7C3, was reported to prevent neuronal degeneration in amyotrophic lateral sclerosis and Parkinson’s disease models, strongly suggesting that NAMPT may play a key role in neurodegenerative diseases." (PMID 33036437, 2020).
periodontitis (6 papers, 2013 to 2026). An acute or chronic inflammatory process that affects the tissues that surround and support the teeth. "Since MMP-1 and CCL2 are molecules known to be strongly associated with periodontitis, we further studied their regulation by NAMPT." (PMID 24058270, 2013). "Nonetheless, periodontal diseases are caused by a complex bacterial biofilm and further studies should clarify whether other microorganisms, which are associated with periodontitis, also stimulate the synthesis of NAMPT in HGF." (PMID 24707118, 2014). "Obese individuals have an increased risk of periodontitis, and elevated circulating levels of nicotinamide phosphoribosyltransferase (NAMPT) may be a pathomechanistic link between both diseases." (PMID 24288440, 2013). "Obese individuals have an increased risk of periodontitis, and elevated circulating levels of adipokines, such as nicotinamide phosphoribosyltransferase (NAMPT), may be a pathomechanistic link between both diseases." (PMID 24058270, 2013). "Nicotinamide phosphoribosyltransferase (NAMPT) protein expression was significantly upregulated in endothelial cells within periodontitis tissues, with levels increasing as the disease progressed." (PMID 40303304, 2025). "Our study showed that NAMPT was highly expressed in the endothelial cells in periodontitis gingival compared with the healthy." (PMID 40303304, 2025). "Next we studied the expression of NAMPT as well as other adipokines and their receptors in gingival biopsies from periodontally healthy, gingivitis, and periodontitis subjects." (PMID 24707118, 2014). "The expression of NAMPT was significantly enhanced in gingiva from periodontitis patients as compared to gingiva from periodontally healthy subjects." (PMID 24707118, 2014). "Additionally, NAMPT was significantly upregulated in the endothelial cell subpopulation of periodontitis and positively correlated with TEM." (PMID 40303304, 2025). "NAMPT expression was significantly elevated in periodontitis mice compared to healthy controls." (PMID 40303304, 2025). "Collectively, these observations suggest that interfering NAMPT-mediated lipid synthesis might be a novel therapeutic target for periodontitis." (PMID 40303304, 2025). "Thus, to further confirm the effect of NAMPT, we examined its expression in mice and patients with periodontitis using IHC staining." (PMID 40303304, 2025). "Overall, these results suggest that NAMPT is highly expressed in endothelial cells during periodontitis and may play a key role in modulating the TEM process in the disease." (PMID 40303304, 2025). "Moreover, in clinical samples from patients at different stages of periodontitis, NAMPT levels showed a progressive increase in accordance with disease severity." (PMID 40303304, 2025). "Consistent with this view, we hypothesize that NAMPT may play a role in increased vascular permeability in periodontitis." (PMID 40303304, 2025). "Interestingly, the present study found the NAMPT protein level unaltered in the gingival tissues of rats with periodontitis." (PMID 35481344, 2022). "Local synthesis of NAMPT in the inflamed gingiva may contribute to the enhanced gingival and serum levels of NAMPT, as observed in periodontitis patients." (PMID 24707118, 2014). "In order to verify the results from our in vitro experiments, in which inflammatory and infectious conditions were simulated, we also studied the expression and protein levels of NAMPT in gingival biopsies from periodontally healthy, gingivitis, and periodontitis subjects." (PMID 24707118, 2014). "However, the role of nicotinamide phosphoribosyltransferase (NAMPT) in macrophage regulation within periodontitis remains unclear." (PMID 41969528, 2026). "In addition, although NAMPT could be induced by P. gingivalis in periodontitis, P. gingivalis was aggregated in a small area of gingival tissue." (PMID 35481344, 2022).